BRCA2 (BRCA2 DNA repair associated)
Diseases named in the same sentence as BRCA2 in open-access papers (continued):
Sharing a sentence is not in itself a finding about the gene and the disease.
prostate carcinoma (continued). "A recent meta-analysis on BRCA-associated prostate cancer risk and mortality also reported an increased mortality in BRCA2 carriers and concluded that BRCA2 but not BRCA1 mutations were associated with higher prostate cancer mortality." (PMID 34575694, 2021). "The risk of prostate cancer in male carriers of BRCA1 variants is approximately equivalent to the general population’s risk, but the phenotype of such cancers, as well as the therapeutic approach, is similar to that of carriers of BRCA2 variants." (PMID 34771713, 2021). "In a multinational study of 6500 male patients with BRCA1 and BRCA2 pathogenic sequence variants (PSV), two regions in BRCA2 (c.756-c 1000 and c.7914þ) were identified as high risk for developing Gleason 8b prostate cancer—this was more prominent in PSVs in PCCRs." (PMID 34884434, 2021). "Germline or somatic mutations in DNA damage repair (DDR) genes, such as BRCA2, CHEK2, ATM, RAD51D, BRCA1, and PALB2, have been described in around 20–25% of advanced prostate cancer patients, which involved in aggressive disease and poor outcomes in these patients." (PMID 33413230, 2021). "In the present analysis we expanded the findings and suggest that BRCA2 could explain the association of early onset ALL with breast and prostate cancers." (PMID 34117277, 2021). "We consider it to be inappropriate to treat a woman with DCIS or a man with prostate cancer expectantly without first ruling out a BRCA1 or BRCA2 mutation." (PMID 33920818, 2021). "In this study, we have screened 30 familial prostate cancer patients for BRCA1 and BRCA2 mutations." (PMID 34242281, 2021). "Based on previously estimated population frequencies of BRCA1 and BRCA2 mutations, it was estimated that BRCA1 mutations confer a relative risk of prostate cancer of approximately 3.7-fold and 8.6-fold, which translates to an 8.6% and 15% cumulative risk by age 65 years." (PMID 34356066, 2021). "The display of all BRCA2 germline and somatic mutations described in the curated set of non-redundant studies of cBioPortal for Cancer Genomics shows that BRCA2 is altered in 10–15% of breast, ovarian, and prostate cancer cases, whereas BRCA2 is altered in 18% of melanoma cases." (PMID 34065235, 2021). "A recent study evaluating plasma cfDNA from 69 patients with advanced prostate cancer found that up to 10% of patients can have CHIP involving HRR genes (primarily ATM but also BRCA2 and CHEK2), suggesting a need for paired whole‐blood samples as a control to avoid misdiagnosis." (PMID 33630412, 2021). "In prostate cancer, germline BRCA2 variant carriers had worse clinical outcomes than non-variant carriers when treated with surgery or radiotherapy." (PMID 35008774, 2021). "For the expected pathogenic BRCA2 mutation-associated cancer types (including breast, ovarian and prostate cancer), the C-terminal BRCA2 variants have not been found as risk factors." (PMID 33672545, 2021). "The patterns of increased familial cancers suggest that BRCA2 mutations could contribute to associations of ALL with breast and prostate cancers, and mismatch gene PMS2 mutations with rectal and endometrial cancers." (PMID 34117277, 2021). "We found that the proportion of men with aggressive prostate cancer who carried a BRCA2 pathogenic variant exceeded that observed in men with non-aggressive prostate cancer (18/787 carriers, 2.3% and 4/769 carriers, 0.5%, respectively; p = 0.004)." (PMID 33804961, 2021). "A similar finding was reported by the IMPACT study where BRCA2 mutation carriers were associated with a higher incidence of prostate cancer and diagnosed at a younger age as compared to non-carriers." (PMID 34575694, 2021).
prostate carcinoma (continued). "BRCA1 and BRCA2 accounted for 2 patients (100%) in 7 prostate cancer patients." (PMID 33649982, 2021). "Mutations in DNA damage repair pathway genes, including BRCA2 and CHEK2 have also been reported in pancreatic NET48 and may promote tumour sensitivity to LuTate, as reported in BRCA2 mutant prostate cancer treated with Lu-177 PSMA therapy." (PMID 32576907, 2020). "However, deep deletions (primarily of BRCA2) occurred much more frequently in prostate cancer (33%) compared to other cancer types, consistent with previous observations." (PMID 33149131, 2020). "Elevated TILs have also been observed in BRCA1/BRCA2 mutant prostate cancer and breast cancer." (PMID 32612833, 2020). "Here we report a case of a patient with prostate cancer who received a platinum agent and PARP inhibitor sequentially and in whom polyclonal BRCA2 reversion mutations were identified as the likely mechanism of acquired resistance to carboplatin and primary resistance to PARP inhibition." (PMID 32171277, 2020). "However, olaparib-based therapies were tested mainly for breast, ovarian, pancreatic and prostate cancer cases with a mutation in high-penetrance genes BRCA1 and BRCA2." (PMID 32252452, 2020). "Further, a patient with BRCA2 mutant MSS prostate cancer was reported to be sensitive to ICB." (PMID 32612833, 2020). "In addition, metastases derived from castration-resistant prostate cancers, besides showing AR amplification, display also frequent somatic deletions of the BRCA2 gene." (PMID 31284411, 2019). "Instead, olaparib decreased AR levels only in BRCA2-knockdown prostate cancer cells." (PMID 31284411, 2019). "We report here that castration-resistant prostate cancer cells defective in BRCA2 are hypersensitive to 6-TG at levels comparable to olaparib treatment, and that this could be reversed by transient transfection of a vector expressing BRCA2." (PMID 31284411, 2019). "PNT1A normal prostate cells express higher BRCA2 levels than prostate cancer cells." (PMID 31284411, 2019). "Familial clustering of prostate cancers was reported and ~5% of cases of prostate cancer could be directly related to highly penetrant mutations at the level of BRCA1, BRCA2, and HOXB13." (PMID 31366128, 2019). "In addition, PCAT1 is a long non-coding RNA, which is known to be upregulated in prostate cancer and negatively regulates BRCA2 expression while positively affecting MYC expression." (PMID 31748536, 2019). "Since BRCA2 expression conferred resistance to 6-TG-induced apoptosis in castration-resistant prostate cancer cells, we then tested whether 6-TG analogues may have an effect on BRCA2-proficient prostate cancer cells." (PMID 31284411, 2019). "Similarly, rescue of BRCA2 levels in BRCA2 shRNA-expressing prostate cancer cells resulted in resistance to 6-TG, PTX and olaparib." (PMID 31284411, 2019). "Importantly, the HRR abnormalities are observed in 31% of advanced prostate cancers and include: BRCA2 (9.8%), CDK12 (5.6%), ATM (5.2%), CHEK2 (1.8%), BRCA1 (1.4%) FANCA (1.3%), and ATR (1.1%)." (PMID 31366128, 2019). "Though a BRCA2 mutation was strongly suspected in this case based on the history of the patient (diagnosis with high-grade histology and advanced-stage breast and prostate cancer), genetic testing was not available 20 years ago." (PMID 30577860, 2018). "BRCA1 and BRCA2 are genes centrally involved in this process, and mutations resulting in damaged BRCA1 or BRCA2 proteins can lead to various types of cancer such as breast, ovarian, or prostate cancer among the most closely associated." (PMID 30103829, 2018). "We used two prostate carcinoma cell lines: 22RV1, which has known deleterious BRCA2 mutations, and DU145, which does not have known deleterious mutations in either BRCA1 or BRCA2." (PMID 30486888, 2018).
prostate carcinoma (continued). "For example, prostate cancer risk by age 80 years at the 5th and 95th percentiles of the PRS varies from 7% to 26% for carriers of BRCA1 mutations and from 19% to 61% for carriers of BRCA2 mutations, respectively." (PMID 28448241, 2017). "This showed that just over 1% of men who developed prostate cancer below age of 65 carried a deleterious BRCA2 mutation and often they did not have a positive family history." (PMID 28031937, 2016). "The results showed that men have a relative risk of prostate cancer of five in those who have a germline BRCA2 mutation compared with men without a mutation." (PMID 28031937, 2016). "Men who are carriers of BRCA2 mutations are at higher risk of developing prostate cancer than non-carriers, and when they are diagnosed with prostate cancer, it tends to be with higher grade, more aggressive disease." (PMID 26258074, 2015). "A small sample of men who possessed a BRCA2 mutation and were diagnosed with prostate cancer at less than 55 years were compared with men diagnosed at a similar age but without a mutated BRCA2 gene." (PMID 26236408, 2015). "Furthermore our group has recently contributed to a study in which a correlation was shown between expression levels of BRCA2 and mitochondrial DNA (mtDNA) in prostate cancer." (PMID 25136623, 2014). "For prostate cancer, we analyzed 5 genes and did not observe an over-representation of SNP associations at p<0.05 (observed/tested: BRCA2, 2/83; ELAC2, 1/9, HOXB13, 0/2; MSR1, 1/22; RNASEL, 2/21)." (PMID 23555315, 2013). "We did not remove any prostate cancer pedigrees from our High-Risk Prostate Cancer Resource because of prior knowledge of a BRCA2 mutation." (PMID 19476645, 2009). "This study adds further evidence that BRCA2 has a limited role in heritable prostate cancer." (PMID 19476645, 2009). "Not all of the patients in our study were proven carriers of a BRCA2 mutation; we included 67 carriers (or obligate carriers) and 116 men with prostate cancer who had not been tested for the presence of the mutation." (PMID 18577985, 2008). "The risk of prostate cancer is elevated approximately fivefold in BRCA2 carriers, compared to noncarriers." (PMID 18577985, 2008). "BRCA1 and BRCA2 have been identified as tumour suppressors for several different hormone-responsive cancer types (breast and prostate cancers (BRCA1 and BRCA2) and endometrial and cervical cancer (BRCA1)) and a non-endocrine cancer type (pancreas cancer (BRCA1 and BRCA2))." (PMID 16434996, 2006). "BRCA2 (and to some extent BRCA1) mutations may explain the findings for pancreatic and prostate cancers." (PMID 15798766, 2005). "BRCA2 deficiency is a well-established predictor for response to PARP inhibition, while concurrent APC mutation—leading to Wnt pathway activation—has been linked to resistance against androgen deprivation and to neuroendocrine differentiation in advanced prostate cancer." (PMID 41395625, 2025). "Therefore, exploring the interrelationships of BRCA1 or BRCA2 with other genes and pathways may offer further assistance in the treatment of BRCA mutation-associated prostate cancer." (PMID 39917165, 2025). "Notably, cases of prostate cancer in patients with BRCA2 mutations are not uncommon in clinical practice." (PMID 39364320, 2024). "Not all pathogenetic variants associated with prostate cancer have the same mutagenic potential, that is, penetrance and a previous expert panel consensus recommendation has advocated for priority testing of BRCA2/1 and DNA mismatch repair (MMR) genes over other variants." (PMID 38439629, 2024). "BRCA2 is estimated to be present in about 1-2% of sporadic prostate cancer cases, leading to an 8.6-fold increase in the risk of prostate cancer, while BRCA1 increases the risk of sporadic prostate cancer by 3.5-fold, but it is present in only 0.44% of prostate cancer cases." (PMID 39364320, 2024).
prostate carcinoma (continued). "Prostate cancer patients with germline BRCA2 mutations exhibit poorer survival outcomes compared to noncarriers, irrespective of whether they receive surgery or radiotherapy as radical treatment." (PMID 38379333, 2024). "The prevalence of defects in DNA repair genes, particularly alterations in HRR genes, ranges from 19 to 33% among individuals with prostate cancer, depending on whether primary or metastatic tumor tissue is considered BRCA2 alterations emerge as the most prevalent in metastatic disease." (PMID 39172235, 2024). "The efficacy of PARP inhibitors as a therapeutic option in prostate cancer is achieved through a “synthetic lethality” process with a simultaneous loss of double-stranded DNA repair function by homologous recombination (HR), in which BRCA1/BRCA2 proteins play an essential role." (PMID 37240284, 2023). "In August 2023, niraparib (not yet approved for prostate cancer) was approved in combination with abiraterone for the treatment of patients with deleterious or suspected deleterious BRCA1- or BRCA2-mutated mCRPC, based on the findings of the MAGNITUDE trial (NCT03748641)." (PMID 37829336, 2023). "However, while control (siNEG) cells form Rad51 foci indicative of HR-mediated repair, cells with siRNA-mediated depletion of PALB2 or BARD1 resemble BRCA2-deficient cells and fail to form Rad51 foci, suggesting that PALB2 or BARD1 loss is sufficient to confer HR deficiency in prostate cancer cells." (PMID 35768576, 2022). "The GALAHAD trial enrolled 165 metastatic castration-resistant prostate cancer patients with germline pathogenic or somatic biallelic pathogenic alterations in BRCA1 or BRCA2 (BRCA cohort), or in other prespecified DDR genes (non-BRCA cohort), who were treated with niraparib 300 mg twice daily." (PMID 36010882, 2022). "PALB2 (Partner and Localizer of BRCA2) mediates the interaction between BRCA1 and BRCA2, plays a role in the nuclear localization of BRCA2, aids in RAD51 loading at resected DNA breaks, and pathogenic mutations in PALB2 have been found to predispose to breast, ovarian, and prostate cancer." (PMID 34065235, 2021). "In fact, previous studies have identified some single-nucleotide polymorphisms associated with prostate cancer risk including c.442-34C>T (rs799923), c.1067A>G (rs1799950), c.4837A>T (rs1799966), c.4357+117G>C (rs3737559) for BRCA1 gene and c.1114A>C (rs144848) for BRCA2 gene." (PMID 34242281, 2021). "In 2015, The Cancer Genome Atlas Research Network reported findings from 333 primary prostate cancers which resulted in the identification of 19% of primary tumors with mutations in DNA repair genes, including 3% in the homologous recombination repair (HRR) gene, BRCA2." (PMID 34073818, 2021). "Herein, we addressed the question whether changes in BRCA2 expression, a potential surrogate marker for BRCA2 activity, may affect the response of castration-resistant prostate cancer cells to 6-thioguanine (6-TG), a thiopurine used in the treatment of haematological malignancies." (PMID 31284411, 2019).
prostate carcinoma (continued). "Notably, overexpression of BRCA2 resulted in resistance of castration-resistant prostate cancer cells to 6-TG-, taxane- and olaparib-based treatment but promoted sensitivity to apoptosis induced by 2-amino-6-bromopurine and 2,6–dithiopurine, two 6-TG analogues." (PMID 31284411, 2019). "Interestingly, BRCA2-mutant prostate tumors more frequently display amplification of region located on chromosome 3q, encoding the WNT pathway modulator MED12L than sporadic prostate cancers." (PMID 31366128, 2019). "Notably, overexpression of BRCA2 abolished any effects on prostate cancer cell proliferation in response to any compound tested and sensitized PC cells to apoptosis following treatment with 2-N-6-BP and 2,6-DTP (174% ± 12 and 187% ± 13, respectively, compared to untreated cells; p < 0.01)." (PMID 31284411, 2019). "However, until phase III trials are completed, the genes other than BRCA1/BRCA2 that could be considered predictive for PARP inhibitor response in advanced prostate cancer will likely remain unknown." (PMID 31242618, 2019). "Most BRCA mutations identified in patients with prostate cancer are somatic, and, compared with low mutation levels in early prostate cancer, ∼15% of patients with metastatic androgen therapy–resistant prostate cancer harbor functionally relevant somatic mutations or deletions in BRCA1 or BRCA2." (PMID 28487881, 2017). "While a few genes such as BRCA2 and HOXB13 are definitively linked to prostate cancer risk in specific patient populations, a greater proportion of prostate cancer risk may be associated with common alleles of low-to-intermediate penetrance or private alleles in families contributing to cancer risk." (PMID 26485759, 2015). "Interestingly in BRCA2, the biologically uncharacterized sites Ser1923 and Thr3193 identified from a general mass spectrometry screen in prostate cancer cells and non-small cell lung cancer from the CST research group are also predicted to be phosphorylated by the CK2 kinases." (PMID 23704879, 2013). "We examined the potential involvement of BRCA2 in a set offive high-risk prostate cancer pedigrees in which all prostate cases were no more distantly related than two meioses from another case, and the resulting cluster contained at least four prostate cancer cases." (PMID 19476645, 2009). "The basis for the aggressive behaviour of the BRCA2-associated prostate cancers is not known." (PMID 18577985, 2008). "It will be a matter of considerable interest to see whether or not the men with prostate cancer and a BRCA2 mutation benefit from targeted chemotherapy." (PMID 18577985, 2008). "The lower risk in OCCR mutations (OR=0.52, 95% CI 0.24–1.00) may explain why prostate cancer risk has not been consistently elevated in studies of BRCA2 in AJ." (PMID 17213823, 2007). "However, given the low prevalence of deleterious BRCA2 mutations in the general population, it is unlikely to account for a significant proportion of prostate cancer cases." (PMID 15385056, 2004). "Among prostate cancer patients carrying BRCA1/2 gPVs, all individuals with high-grade or metastatic disease carried BRCA2 gPVs." (PMID 41970070, 2026). "Poly(ADP-ribose) polymerase inhibitors (PARPi) have reshaped therapy for advanced prostate cancer, yet durable benefit remains concentrated in BRCA1/2-altered tumors, especially BRCA2, and most responders eventually relapse." (PMID 41972679, 2026). "BRCA2, DAB2IP, and the DNA-PKcs inhibitor NU7441 are prostate cancer-related markers, while the methylation of ESR1 and MYOD1 and expression of SEPT9 correlate with radiotherapy response in cervical cancer." (PMID 40277781, 2025). "In the absence of HR-deficient human prostate cancer cell lines suitable for screening, we chose to model BRCA2 deficiency through Cre-mediated deletion in primary mouse prostate organoids freshly isolated from Brca2fl/fl mice (Brca2-null, deletion of N-terminal exons 3-4)." (PMID 40460119, 2025).